MIR4692 (microRNA 4692)
Synonyms: hsa-mir-4692
Gene: MicroRNA gene on chromosome 11 (72,783,530 to 72,783,592, forward strand). Ensembl gene ENSG00000265064.
Homologues: Orthologues: chimpanzee MIR4692 (100% identical).